IFITM3 (interferon induced transmembrane protein 3)
Diseases named in the same sentence as IFITM3 in open-access papers (continued):
Sharing a sentence is not in itself a finding about the gene and the disease.
brucellosis (1 paper, 2024). Brucellosis is a bacterial infection that spreads from animals to people via unpasteurized dairy products or by exposure to contaminated animal products or infected animals. "In brucellosis patients, the expression levels of many typical IFN‐γ/IFN‐I response genes, including IFITM3, B2M, GBP1, IRF1, IFI30, IFNGR2, and so forth, were higher than those in controls." (PMID 39135683, 2024).
cerebral malaria (1 paper, 2013). A sequestration of Plasmodium falciparum in the brain, which can cause coma and/or seizures. "Our work shows IFITM3 is not an ISG involved in the pathogenesis of experimental cerebral malaria." (PMID 24278312, 2013).
chronic viral hepatitis (1 paper, 2025). "In line with a constitutive ISG expression in NK cells, we also showed that the expression of IFITM3, IRF1, IFIT2 and ISG20 are refractory to IFN stimulation in vitro in NK cells that were obtained from patients with HD and chronic viral hepatitis." (PMID 40837234, 2025).
Crohn disease (1 paper, 2021). A gastrointestinal disorder characterized by chronic inflammation involving all layers of the intestinal wall, noncaseating granulomas affecting the intestinal wall and regional lymph nodes, and transmural fibrosis. "Differential expression of IFITM3 has been found in endoscopic biopsies from Crohn’s Disease patients." (PMID 33799418, 2021).
depression (1 paper, 2024). "Notably, a substantial number of upregulated genes associated with depression were identified, such as Ctss, Ifitm3, H2‐K1, Vim, Bst2, Lag3, Cd74, Isg15, Gbp3, and Cxcl10." (PMID 38946585, 2024).
Dysmenorrhea (1 paper, 2024). Pain during menstruation that interferes with daily activities. "COX-2 is an important factor regulating the occurrence of dysmenorrhea symptoms, and IFITM3, as a downstream factor of COX-2, may be regulated by COX-2, so IFITM3 may be related to dysmenorrhea symptoms." (PMID 38239300, 2024). "The relationship between dysmenorrhea and expression of COX-2, WBP2, IFITM3, and SFRP4." (PMID 38239300, 2024).
Flavivirus Infections (1 paper, 2021). Infections with viruses of the genus FLAVIVIRUS, family FLAVIVIRIDAE. "According to a previous study involving flavivirus infection, the mRNA levels of six key ISGs, i.e., IFITM1, IFITM3, OASL2, PKR, VIPERIN, and ISG15, were analyzed by real-time PCR in the spleen and liver." (PMID 35310394, 2021).
fungal infections (1 paper, 2020). "We also found that amphotericin B, an antibiotic used for treatment of patients with severe fungal infections and leishmaniasis, significantly promoted SL-CoV spike-driven infection by disrupting IFITM3-mediated restriction." (PMID 32602823, 2020). "Interestingly, we found that AmphoB, an anti-mycotic drug commonly used for systemic fungal infections, could dramatically enhanced the cell entry of SARS-CoVs and SL-CoVs, and completely blocked IFITM3-mediated restriction, but did not affect IFITM1-mediated restriction." (PMID 32602823, 2020).
H1N1 influenza A (1 paper, 2020). "The rs12252 SNP, which is located on the splicing receptor, is related to the truncated form of the IFITM3 protein and is associated with the severity of the 2009 H1N1 influenza A pandemic and COVID-19." (PMID 33396837, 2020). "According to the allele of the rs34481144 SNP, transcriptional up/down regulation via binding affinity of the transcription factor of the IFITM3 gene is modified and is associated with the severity of 2009 pandemic H1N1 influenza A." (PMID 33396837, 2020).
head and neck cancer (1 paper, 2024). A primary or metastatic malignant neoplasm affecting the head and neck. "IFIT1 and IFITM3 are highly expressed and associated with poor prognosis in head and neck cancer." (PMID 39329063, 2024).
hemorrhagic fever with renal syndrome (1 paper, 2024). A viral infectious disease that is a hemorrhagic fever, located_in kidney, has_material_basis_in Hantaan virus, has_material_basis_in Dobrava-Belgrade virus, has_material_basis_in Seoul virus, or has_material_basis_in Puumala virus, which are carried and transmitted_by rodents. "Most importantly, a high frequency of single nucleotide polymorphism (SNP) rs12252 of IFITM3 with impaired antiviral function against HTNV was found in severe hemorrhagic fever with renal syndrome (HFRS) patients." (PMID 38711929, 2024).
Hypertension (1 paper, 2018). The presence of chronic increased pressure in the systemic arterial system. "Although the range of exploration was only of 1 kb, there were genes with many Repeats in the configuration, which those includes genes with medical interest like a Hypertension-Related Calcium-Regulated Gene Protein, or the Interferon-Induced Transmembrane Protein 3; ii." (PMID 30537933, 2018).
hyperuricemia (1 paper, 2021). An abnormally high level of uric acid. "Differentially methylated regions (e.g. HLA-G, IFITM3, PRKAB2) were found in people with hyperuricemia compared to normouricemia in genes relevant for inflammatory cytokine signaling." (PMID 34321071, 2021).
IgA nephropathy (1 paper, 2025). "Recent studies have identified an increased expression of interferon signature genes such as IFI6, IFI44L, and IFITM3 in PBMCs of patients with IgA nephropathy." (PMID 40269956, 2025).
inflammatory bowel disease (1 paper, 2025). A spectrum of small and large bowel inflammatory diseases of unknown etiology. "Cluster 6 was characterized by the expression of the IFN-γ–induced genes Ifitm1, Ifitm2, and Ifitm3, which have been reported to be associated with inflammatory bowel diseases, alongside with the integrin Itgb1." (PMID 40924026, 2025).
ischemic stroke (1 paper, 2022). A stroke disorder caused by obstruction of blood flow to the brain, due to thrombotic (local blood clot formation) or embolic (due to a blood clot or other material traveling from another site) event. "Here, we present evidence that ischemic stroke causes an increase in IFITM3 expression along with increased microglial activation marker genes in aged brains." (PMID 36012150, 2022). "In our study, we detected increased levels of IFITM3 in inflammatory conditions in the brains of aged mice (e.g., ischemic stroke)." (PMID 36012150, 2022). "Thus, we sought to explore the expression of IFITM3 in microglia in response to a range of inflammatory situations in vitro and in the aged brain following ischemic stroke." (PMID 36012150, 2022). "Therefore, we sought to determine if and where ischemic stroke induces expression of IFITM3 protein in the brain." (PMID 36012150, 2022). "In AD, increased expression of IFITM3 is found in astrocytes and neurons where amyloid-beta levels are increased, however, the expression of IFITM3 in stressed microglia in various neurodegenerative diseases such as ischemic stroke has not been examined." (PMID 36012150, 2022).
leprosy (1 paper, 2015). Leprosy is a chronic infectious disease affecting primarily the skin and peripheral nervous system. "The Toll-like receptor gene cluster, shown to modulate the response to Yersinia pestis and its member TLR1 involved in leprosy susceptibility, were also identified as well as the IFITM3 gene, whose expression was demonstrated to protect against influenza A infection." (PMID 26553317, 2015).
Lymphatic Metastasis (1 paper, 2015). Transfer of a neoplasm from its primary site to lymph nodes or to distant parts of the body by way of the lymphatic system. "Patients with early T status and low expression of IFITM3 may have a lower recurrence risk of lymphatic metastasis." (PMID 26539332, 2015).
mantle cell lymphoma (1 paper, 2024). Mantle cell lymphoma is a rare form of malignant non-Hodgkin lymphoma affecting B lymphocytes in the lymph nodes in a region called the ``mantle zone''. "IFITM3 encodes an IFNγ-induced protein which has been suggested to play a role in tumor progression of multiple cancers including B-ALL, mantle cell lymphoma, colorectal, prostate, and hepatocellular carcinoma." (PMID 38418901, 2024).
multiple myeloma (1 paper, 2022). "Interestingly, platelets from patients with multiple myeloma or myeloproliferative disorders had significantly increased IFITM3 expression, suggesting IFITM3 may also promote thrombotic complications in these patients: a hypothesis to be tested in future studies." (PMID 36194487, 2022).
mycoplasma infection (1 paper, 2023). "To evaluate the impact of IFITM3 on mycoplasma infection, we conducted experiments to measure M. fermentans growth in cells with IFITM3 knockdown." (PMID 37100873, 2023).
myelofibrosis (1 paper, 2022). A partial or complete replacement of the bone marrow stroma by fibrous tissue. "Therefore, these four genes (OAS1, IFITM3, GBP1, and GBP2), especially OAS1, might possess the potential to be novel auxiliary diagnostic and predictive indicators of myelofibrosis, but further research is still necessary in the future." (PMID 36061178, 2022). "Additionally, the four genes (OAS1, IFITM3, GBP1, and GBP2) we identified in this study might have the potential to be auxiliary diagnostic and predictive indicators of myelofibrosis, but further investigations are still necessary in the future." (PMID 36061178, 2022). "The external datasets validated the upregulation of four interferon-related genes (OAS1, IFITM3, GBP1, and GBP2) in JAK2V617F+ myelofibrosis." (PMID 36061178, 2022). "The results showed high AUC values of the four genes (OAS1, IFITM3, GBP1, and GBP2) when distinguishing JAK2V617F+ myelofibrosis from JAK2V617F+ PV or ET." (PMID 36061178, 2022). "Furthermore, we identified four potentially important genes (OAS1, IFITM3, GBP1, and GBP2) that were upregulated uniquely in myelofibrosis." (PMID 36061178, 2022). "Overall, the four interferon-stimulated genes (OAS1, IFITM3, GBP1, and GBP2) exclusively upregulated in myelofibrosis might not only provide important novel clues to the MPN field but also offer special insights into the effects of IFN signaling on the pathogenesis of myelofibrosis." (PMID 36061178, 2022).
myopia (1 paper, 2025). "Macrophages in the myopia group upregulated proinflammatory Ifitm3/6, Apoc1, and Bst2-Siglech in the large intestine, proinflammatory ly6c1, Apoc1, and S100a in the liver, and ly6c1 and S100a in the kidney." (PMID 41330940, 2025).
nephritis (1 paper, 2023). Inflammation of renal tissue. "IFITM2 and IFITM3 showed up-regulation in urine PTCs, suggesting their potential as nephritis markers." (PMID 38077419, 2023).
osteoarthritis (1 paper, 2024). A noninflammatory degenerative joint disease occurring chiefly in older persons, characterized by degeneration of the articular cartilage, hypertrophy of bone at the margins and changes in the synovial membrane. "While we compared PBMC samples between patients with RA stratified by disease activity and healthy controls, upregulation of IFITM3 shown by Zhang and colleagues was only shown in synovial samples from leukocyte-rich RA compared with control samples obtained from patients with osteoarthritis." (PMID 38954480, 2024).
osteosarcoma (1 paper, 2020). A usually aggressive malignant bone-forming mesenchymal neoplasm, predominantly affecting adolescents and young adults. "Five of the seven immune-related genes (CDCA7, GZMA, SLC7A7, VAMP8, and EVI2B) were highly expressed in the osteosarcoma group, while two of these immune-related genes (IFITM3 and ACTA2) were lowly expressed." (PMID 33384961, 2020). "The heatmap of these seven immune-related genes expression level in GSE42352 indicated that five of these genes (CDCA7, GZMA, SLC7A7, VAMP8, and EVI2B) were highly expressed in the osteosarcoma group, but two of these genes (IFITM3 and ACTA2) were highly expressed in the normal group." (PMID 33384961, 2020).
pancreatic cancers (1 paper, 2020). "Similarly, miR-497-5p, a tumor-suppressor, is inversely correlated with IFITM3 in pancreatic cancers, suggesting IFITM3 is a downstream target." (PMID 33364194, 2020).
pheochromocytoma (1 paper, 2020). "While, IFITM3 was highly mutated in seminoma, diffuse glioma and pheochromocytoma." (PMID 33061814, 2020).
respiratory syncytial virus infection (1 paper, 2018). "IFITM3 KO mice also showed modest weight loss during respiratory syncytial virus infection that was absent in WT mice, consistent with effects of IFITM3 on this virus in vitro." (PMID 30662816, 2018).
squamous cell carcinoma (1 paper, 2022). A carcinoma arising from squamous epithelial cells. "For this study, a cell model that was engineered in our previous publication is used to investigate the role of IFITMs—SiHa cells originating from squamous cell carcinoma of the cervix which express IFITM1 and IFITM3 at detectable endogenous levels with a higher expression upon IFNγ stimulation." (PMID 36008984, 2022).
thrombosis (1 paper, 2022). "To determine whether there was a relevant in vivo function for the upregulation of platelet IFITM3, we utilized 2 platelet-dependent thrombosis models." (PMID 36194487, 2022).
infection (223 papers, 2007 to 2026). The state of being infected such as from the introduction of a foreign agent such as serum, vaccine, antigenic substance or organism. "Another study looking at patients with either H7N9 or 2009 H1N1 infections observed that those carrying the rs12252-C SNP faced a higher risk of death, emphasizing the critical role of IFITM3 in controlling severe outcomes of emergent infections." (PMID 40237465, 2025). "Recent work from our group shows that IFITM3 deficiency not only increases the severity of influenza virus infections, but it also lowers the infectious dose needed to establish a productive infection with zoonotic viruses." (PMID 40237465, 2025). "Collectively, these cohorts illustrate how IFITM3 SNPs are associated with severe outcomes in scenarios where innate immunity is the primary early defense against infection." (PMID 40237465, 2025). "The study shows that mutations in the IFITM3 gene lead to elevated sensitivity of human embryonic lung fibroblast subline WI-38 VA13 to infection with an influenza virus." (PMID 38203797, 2024). "Overall, these data demonstrate that IFITM3 deficiency broadly increases infection of human cells with influenza viruses of animal origin." (PMID 39477971, 2024). "The Omicron variant had decreased cleavage efficiency in certain cell types and increased susceptibility to IFITM2 and IFITM3, possibly contributing to the milder disease states seen with Omicron infections." (PMID 37985854, 2024). "Specifically, we show that IFITM3 underlies sterilizing immunity that prevents infection at low influenza virus doses that are below a minimum threshold." (PMID 39477971, 2024). "The proinflammatory cytokine IL-6 can strongly induce increased expression of IFITM3, and infection of IFITM3-deficient mice with cytomegalovirus resulted in higher levels of IL-6 production." (PMID 37602193, 2023). "As a result, A549 cells, in which NDFIP2 has been genetically removed by CRISPR/Cas9, exhibit lower levels of IFITM3 and become highly susceptible to infection." (PMID 37896772, 2023). "For IAV, the overexpression of IFITM2 and IFITM3 was associated with a significant reduction in infected cells at 8 h post-infection (assessed by intracellular staining for the viral nucleoprotein (NP) protein,)." (PMID 37111405, 2023). "Genetic deficiency of MyD88 in Ifitm3−/− mice resolved infection-induced weight loss to wt levels, indicating that signalling through MyD88 is required to drive exacerbated weight loss in Ifitm3−/− mice." (PMID 36075894, 2022). "IFITM3 KO mice thus experience increased cellular infection and viral spread in the lung, spleen, and heart, organs that are naturally susceptible to infection in WT mice." (PMID 35544568, 2022). "In contrast, monocytes treated with an IFITM3-specific siRNA showed a loss of viral restriction, since HK and HK-R2 showed higher infection rates and reached the infectivity of HK-H17R." (PMID 35359920, 2022). "The interferon-induced transmembrane protein 3 (IFITM3), a small molecule transmembrane protein induced by interferon, is generally conserved in vertebrates, which can inhibit infection by a diverse range of pathogenic viruses such as influenza virus." (PMID 35769480, 2022). "The infection of HeLa cells with influenza virus showed that a decrease in the expression of IFITM2 or IFITM3 increased the cell susceptibility to the virus by about two or four times, respectively, compared with control cells." (PMID 35216030, 2022). "Expression of IFITM3 renders target cells less susceptible to infection by cell-free HIV-1 particles, but cell-to-cell transmission of HIV-1 partially escapes this antiviral effect." (PMID 34078739, 2021). "IFITM3 was validated as a flavivirus antiviral factor upon infection with pathogenic WNV and DENV-2." (PMID 34020727, 2021). "Previous studies have reported that the rs12252 C allele of the IFITM3 gene was associated with the severity of infection for the influenza A H1N1 2009 pandemic virus." (PMID 35056363, 2021).